KCNJ11 (potassium inwardly rectifying channel subfamily J member 11)
Diseases named in the same sentence as KCNJ11 in open-access papers (continued):
Sharing a sentence is not in itself a finding about the gene and the disease.
diabetes (continued). "Before that, there were two reports about KCNJ11 mutation causing diabetes." (PMID 34465386, 2021). "Since our study had excluded patients with a personal or a family history of NDM, it confirmed that ABCC8/KCNJ11 variants can cause a milder form of diabetes that may reveal as adult-onset diabetes." (PMID 31291970, 2019). "We hypothesized that there could be a gene-by-environment interaction between KCNJ11 variation and serum K on diabetes risk." (PMID 30169531, 2018). "We hypothesized that the potential impact of low-normal serum K on incident diabetes risk may be stronger among people with an increased risk of diabetes due to KCNJ11 variants." (PMID 30169531, 2018). "Variants in KCNJ11 are associated with increased diabetes risk." (PMID 30169531, 2018). "Mutations in KCNJ11 lead to a permanent opening of the potassium channel in the pancreatic b cells, thus preventing any activation of voltage-dependent calcium channel and glucose-induced insulin secretion leading to diabetes." (PMID 28766502, 2018). "In addition to diabetes, patients with KCNJ11 mutations have CNS features, owing to expression of KCNJ11 in the brain, as well as the pancreas." (PMID 29880308, 2018). "Thus, the aim of this study was to explore the effects of a wide range of KCNJ11 mutations, and of diabetes duration, in a large sample (n = 127) of patients who attempted to transfer to sulfonylureas from insulin." (PMID 27033559, 2016). "The two patients with KCNJ11 mutations presented with diabetes between 1 and 3 months of age." (PMID 25755231, 2015). "Inactivating or activating mutations in one of the two subunits forming this channel, i.e., the sulfonylurea receptor-1 gene (SUR1, ABCC8) or the inward rectifier K+ channel (Kir6.2, KCNJ11), cause congenital hyperinsulinemic hypoglycemia and diabetes in neonates and infants." (PMID 26400961, 2015). "Therefore, in this study, we analyzed the E23K polymorphism of KCNJ11 gene in a group of subjects with T2D and a group of controls identified in a nationwide surveillance program for diabetes in schoolchildren aged 6~18 in Taiwan." (PMID 25309595, 2014). "As the mutation in KCNJ11 is clinically important and there is a proven response to sulfonyurea, it is mandatory to screen patients presenting with diabetes in the first six months, because it will have a major impact on the type of therapy, glycemic control, and quality of life." (PMID 20220270, 2010). "We aimed to characterise the possible longitudinal associations of common diabetes-susceptibility variants in the KCNJ11, PPARG, TCF7L2, IGF2BP2, CDKAL1, SLC30A8 and HHEX gene loci, with fasting glucose level; and of an obesity-associated variant in the FTO gene, with body mass index (BMI)." (PMID 20929593, 2010). "That effect size would be comparable to the role of known diabetes genes including the potassium channel gene KCNJ11 E23K variant, or peroxisome proliferator activating receptor γ (PPARG) P12A variant, or more recently described variants that have required very large populations to confirm." (PMID 18366646, 2008). "Even within the same family, individuals carrying the same pathogenic KCNJ11 mutation may exhibit significant variability in age of onset and disease severity; while some develop diabetes in the neonatal period, others may present later in life with a milder, MODY-like phenotype." (PMID 41367630, 2025). "However, there have been reports of other inactivating KCNJ11 mutations leading to diabetes." (PMID 38152125, 2023). "Patients with the E227K mutation in the KCNJ11 gene typically manifest with transient neonatal diabetes, which remits spontaneously, usually within 4–60 weeks of onset; however, more than half of these patients relapse into permanent diabetes in adolescence or early adulthood." (PMID 35837280, 2022).
diabetes (continued). "Finally, genes involved in monogenic diabetes may also be implicated in polygenic disease, for example, activating mutations in KCNJ11 causes neonatal diabetes whilst the common E23K variant in KCNJ11 has been associated with T2D susceptibility." (PMID 30599002, 2018). "Based on the studies above, it is clear that further investigation is needed to determine the characteristics of people, whether demographic, anthropometric, clinical, or even genetic factors other than KCNJ11 variants, whose diabetes risk could most be affected by low-normal serum K." (PMID 30169531, 2018). "Finally, the example of single gene diabetes, particularly HNF1A MODY and permanent neonatal diabetes associated with the KCNJ11 and ABCC8 genes, all efficiently controlled on sulfonylurea, inspires us to continue the efforts to tailor individual treatment for T2DM patients." (PMID 22996131, 2012). "The molecular characterization of KCNJ11 and ABCC8 mutations has arguably provided the most significant success story in precision medicine for diabetes." (PMID 41614934, 2026). "While GoF mutations cause diabetes via hyperpolarization, loss-of-function (LoF) mutations in ABCC8 or KCNJ11 traditionally result in the opposite phenotype: congenital hyperinsulinism (CHI)." (PMID 41614934, 2026). "KCNJ11 mutations can present with a broad clinical spectrum, including transient or permanent neonatal diabetes, MODY-like diabetes in childhood or early adulthood, type 2 diabetes phenotypes, and congenital hyperinsulinism." (PMID 41367630, 2025). "This intrafamilial heterogeneity underscores the variable expressivity and incomplete penetrance of KCNJ11-related diabetes, highlighting the need for individualized clinical evaluation and long-term follow-up." (PMID 41367630, 2025). "The efficacy of sulfonylureas in patients with KCNJ11-related diabetes has been well established, with studies demonstrating successful transition from insulin to oral therapy in the majority of cases." (PMID 41367630, 2025). "In their study, the genes GCKR, KCNJ11, and TCF7 were associated with hypertriglyceridemia and diabetes, while the LPIN1 and SLC22A1 genes were linked to a favorable response to antidiabetic drugs like rosiglitazone and metformin." (PMID 39408795, 2024). "A recent study of the diabetes prospective follow‐up (DPV) initiative analyzed individuals with ABCC8‐MODY or KCNJ11‐MODY and reported a switch from insulin to oral sulfonylureas in most persons while maintaining good metabolic control." (PMID 39511990, 2024). "Experts now prefer to simply using the gene names for clarity, such as KCNJ11 diabetes (or KCNJ11‐MODY, but in this paper we still use MODY13).With the development of clinical molecular diagnostic technologies, the typing of MODY is changing." (PMID 38095268, 2024). "The benign trajectory of diabetes due to pathogenic GCK mutations, and the sulfonylurea-hyperresponsiveness conferred by activating KCNJ11 or ABCC8 mutations, or loss-of-function HNF1A or HNF4A mutations, often decisively guide clinical management." (PMID 35618782, 2022). "Numerous studies have examined the polymorphisms in the KCNJ11 and KCNQ1 genes as the risk factors for type 2 diabetes mellitus; nevertheless, the results of the studies are inconsistent and are different in various populations." (PMID 35893051, 2022). "Comparison of clinical characteristics of children with diabetes caused by a mutation in INS, KCNJ11, or ABCC8." (PMID 35518939, 2022). "A young female patient, diagnosed with diabetes mellitus at the age of 28 years old in 2009, carries KCNJ11 R136C by whole exome sequencing and her daughter doesn’t carry this mutation." (PMID 34465386, 2021). "It is essential to perform rapid genetic testing for ABCC8/KCNJ11 in any patient diagnosed with diabetes before 6 months of age, particularly given issues regarding access to and cost of insulin in some populations." (PMID 34566892, 2021).
diabetes (continued). "SUR1 also co-associates with the pore-forming subunit, KIR6.2/Kcnj11, an ATP-sensitive potassium channel, to form KATP channels, whose role has historically been extensively studied in pancreatic β cells and diabetes mellitus." (PMID 34769328, 2021). "Four members in a three-generation Japanese family carried KCNJ11 C42R and were diagnosed with diabetes, three cases of which were diagnosed at the age of 3, 22 and 26 years old." (PMID 34465386, 2021). "In humans, the significance of KCNJ11 in insulin secretion was suggested by its function in permanent neonatal diabetes and familial persistent hyperinsulinemic hypoglycaemia of infancy." (PMID 33101408, 2020). "Variants in the genes encoding Kir6.2 and SUR1, KCNJ11 and ABCC8, are commonly associated with insulin secretion disorders and diabetes and many of these variants cause trafficking defects of KATP channels." (PMID 31934859, 2020). "KCNJ11 and ABCC8 gain-of-function mutations relate to a rare type of diabetes mellitus, which arises before the first year of life: neonatal diabetes mellitus." (PMID 29534462, 2018). "KCNJ11 PNDM is a good example of how human molecular genetics has driven the application of precision medicine in diabetes." (PMID 30599002, 2018). "One meta-analysis assessed the significance of the presence of KCNJ11 rs5215 among African Americans with similar results [adjusted OR (95% CI) of incident diabetes of 1.16 (1.09, 1.23)]." (PMID 30169531, 2018). "The presence of neurological features in this type of diabetes is due to expression of KCNJ11 in KATP channels in several brain regions as well as the pancreas." (PMID 30599002, 2018). "As for the genetic susceptibility for diabetes, ABCC8/KCNJ11 is associated with neonatal diabetes, GATA6 is associated with pancreas agenesis, and HNF1A is associated with monogenic diabetes." (PMID 28744848, 2017). "Participants with six different genetic aetiologies were assessed, including two with a KCNJ11 or ABCC8 mutation, which account for >40% of all reported neonatal diabetes diagnoses." (PMID 28779213, 2017). "This study examined the association of the polymorphic markers of the genes KCNJ11, SLC30A8, CDKAL1, CDKN2B and FTO with type 2 diabetes mellitus in Russia." (PMID 28717589, 2017). "The genes ABCC8 and KCNJ11 have received intense focus in type 2 diabetes mellitus (T2DM) research over the past two decades." (PMID 25955821, 2015). "This patient was misdiagnosed as type 1 diabetes mellitus and the confirmation of KCNJ11 NDM was done at the age of 6.2 years." (PMID 25755231, 2015). "In permanent neonatal diabetes (PNDM) patients, homozygous GCK (n=6), EIF2AK3 (n=3), PTF1A (n=3), and INS (n=1) and heterozygous KCNJ11 (n=2) mutations were identified." (PMID 25755231, 2015). "This phenotypic spectrum of diabetes has also been reported in carriers of a mutation in ABCC8 or in the insulin (INS) gene, which both represent, with KCNJ11, the most frequently mutated genes in patients with NDM." (PMID 22701567, 2012). "In this form of KCNJ11-related PNDM, SU action precisely corrects the mechanism underlying this type of diabetes by closing the activated potassium channel of the beta cells." (PMID 22996131, 2012). "KCNJ11 gene screening is currently indicated by guidelines in all patients who present with diabetes diagnosed before 6–12 months of age." (PMID 22701567, 2012). "Beyond neonatal diabetes mellitus (NDM), KCNJ11 is also a MODY gene (‘MODY13’), confirming the wide spectrum of diabetes related phenotypes due to mutations in NDM genes (i.e. KCNJ11, ABCC8 and INS)." (PMID 22701567, 2012). "We have found associations (with p values less than 0.05) for SGA with the diabetes related SNP in KCNJ11 and the obesity related SNPs in FTO, PFKP, PTER, SEC16B and BDNF." (PMID 20712903, 2010).
diabetes (continued). "Some of the genes associated with both monogenic (ABCC8 and KCNJ11) and complex diabetes (KCNJ11, KCNQ1) encode subunits of these potassium channels and accordingly, monogenic diabetes of this type can be well managed with sulfonylureas." (PMID 19794883, 2009). "In our study, we are the first to reveal that targeting KCNJ11/ABCC8 for diabetes treatment could reduce the incidence of PT from a genetic perspective, with gene expression analysis further supporting the role of KCNJ11 in PT." (PMID 41357784, 2025). "Initial targeted sequencing of neonatal diabetes-associated genes (including KCNJ11, ABCC8, INS, and the 6q24 locus) yielded negative results." (PMID 41393705, 2025). "This variant p.(Arg201His) can also cause KCNJ11-MODY with variable onset and severity of diabetes." (PMID 36418577, 2023). "The KCNJ11 and KCNQ1 gene polymorphisms were associated with type 2 diabetes mellitus and GDM." (PMID 35893051, 2022). "Data confirmed that KCNJ11 mutations can be associated with a large spectrum of diabetes phenotypes and cannot completely penetrant as one of the identified members of the French MODY family that carries the KCNJ11 p.Glu227Lys mutation, has normal fasting plasma glucose level at 39 years." (PMID 36361703, 2022). "Case 4 carried a KCNJ11 gene mutation, typically responsible for neonatal diabetes, but heterozygous mutations in this gene rarely cause isolated diabetes in children and adolescents, and some authors recommend that the molecular diagnosis of MODY should include the KCNJ11 gene." (PMID 36294752, 2022). "Two patients were diagnosed with neonatal DM, one with a transient form caused by paternal uniparental disomy of 6q24 and the other with a permanent form with a heterozygous mutation (c.602G > A [p.R201H]) in KCNJ11, leading to developmental delay, epilepsy, and neonatal diabetes (DEND) syndrome." (PMID 33663443, 2021). "First, in KCNJ11 permanent neonatal diabetes there is a fixed β-cell defect that does not change over time, whereas in type 2 diabetes there is a deterioration in β-cell function of about 5% per year of diabetes." (PMID 29880308, 2018). "There have been no studies to determine the impact of the KCNJ11 variants on diabetes risk in the JHS cohort." (PMID 30169531, 2018). "In these analyses of pooled data from ARIC and JHS, we confirmed that serum K is a predictor of incident diabetes, independent of traditional diabetes risk factors and independent of genetic variants of the KCNJ11 gene." (PMID 30169531, 2018). "In multivariable models, serum K continued to be a significant predictor of incident diabetes both without adjustment for the KCNJ11 variants of interest and with adjustment for the KCNJ11 variants of interest (Models 3 and 4)." (PMID 30169531, 2018). "The finding that the presence of KCNJ11 variants was not a significant predictor of diabetes risk in this cohort was not completely unexpected." (PMID 30169531, 2018). "In this cohort, rs5215 and rs5219 of KCNJ11 were not significant predictors of incident diabetes nor effect modifiers of the association between serum K and incident diabetes." (PMID 30169531, 2018). "In particular, the treatment of KCNJ11 neonatal diabetes with sulphonylureas represents the best precision approach in diabetes and illustrates how advances in human molecular genetic techniques have facilitated major discoveries, with huge implications for patient care." (PMID 30599002, 2018). "Parents who carried the same KCNJ11 or ABCC8 mutations showed no neonatal diabetes mellitus symptoms or past history of abnormal glucose metabolism." (PMID 26839896, 2016). "Recent recognition that diabetes before age 6 months is neonatal diabetes and the availability of rapid molecular genetic diagnosis means that almost all patients should now be diagnosed with KCNJ11 diabetes within weeks of diagnosis, thus facilitating a very early transfer." (PMID 27033559, 2016).
diabetes (continued). "The result showed that the E23K genotype of KCNJ11 may be a high risk for subjects with T2DM who have a positive family history of diabetes in comparison to those without a family history of diabetes." (PMID 40352968, 2025). "In this paper, we therefore study the functional effects of a dominant loss-of function KCNJ11 mutation that did not cause detectable hyperinsulinism in infancy but was associated with sulfonylurea-sensitive diabetes in the absence of an autoimmune or other monogenic cause, in early adult life." (PMID 38366195, 2024). "A likely pathogenic KCNJ11 de novo variant (NM_000525.4: c.675C>A, p.Ser225Arg) was identified in a patient who remitted to normal glycemia without any insulin therapy 1 week after diabetes onset." (PMID 38408297, 2024). "However, the identification of genetic causes, in particular, the two main mutations that cause PNDM (KCNJ11 and ABCC8), has led to the development of effective treatment options for many children with this type of diabetes, particularly those with KCNJ11 mutations." (PMID 39457190, 2024). "Also, a genome-wide analysis of the DNA methylation quantitative trait locus (mQTL) in human pancreatic islets revealed 383 CpGs (0.08% of tested CpGsites), showing significant associations including known diabetes loci, e.g., ADCY5, KCNJ11, HLA-DQA1, INS, PDX1 and GRB10." (PMID 38136971, 2023). "ABCC8/KCNJ11 gain-of-function (GOF) mutations cause the permanent opening of the KATP channel, and thus reduce insulin secretion and eventually cause hyperglycemia with a wide spectrum of diabetes phenotypes, ranging from neonatal diabetes to MODY to adult-onset diabetes." (PMID 35052457, 2022). "Furthermore, not all SNPs in KCNJ11 have been specifically associated with altered risk in all types of diabetes." (PMID 36128718, 2022). "In addition to diabetes, KCNJ11-PNMD patients may also have neurological features such as developmental delay and epilepsy (DEND syndrome)." (PMID 34079523, 2021). "While this study of the combined ARIC-JHS cohorts found that KCNJ11 variants are not significant risk factors for diabetes, our findings confirm the previously noted association between serum K and diabetes risk, independent of the presence of the KCNJ11 variants." (PMID 30169531, 2018). "Among participants without diabetes at baseline, we performed multivariable logistic regression to determine the effect of serum K, KCNJ11 variants, and their interactions on the odds of incident diabetes mellitus over 8–9 years in the entire cohort and by race." (PMID 30169531, 2018). "The Kir6.2 protein along with another protein SUR1 encoded by the ABCC8 gene located next to the KCNJ11 gene forms the KATP channel which modulates insulin production and secretion through glucose metabolism and is the target of sulphonylurea drugs used for treating diabetes." (PMID 28330327, 2016). "Importantly, our study firmly confirms that KCNJ11 mutations can be associated with a large spectrum of diabetes phenotypes and can be not totally penetrant." (PMID 22701567, 2012). "Thus, by analogy, it can be concluded that rare severe variants in the CACNA1E gene may cause monogenic diabetes, as is the case with the HNF1β, GCK or KCNJ11 genes, while common single nucleotide alterations are associated with an increased risk of type 2 diabetes." (PMID 38932873, 2024). "In both T1D and T2D, we found enrichment of monogenic forms of diabetes, as expected —2 genes in T1D (RASGRP1, INS) and 8 in T2D (HNF1B, GCK, WFS1, KCNJ11, ABCC8, HNF1A, PPARG, SLC2A2)." (PMID 33836063, 2021). "Therefore, diabetes-related genes KCNJ11 may also be a potential prognostic biomarker of BC." (PMID 34956313, 2021). "Candidate target genes also included six genes involved in MODY and other monogenic and syndromic forms of diabetes (ABCC8, KCNJ11, GCK, INS, GLIS3, WFS1)." (PMID 31064983, 2019). "However, not all studies have found KCNJ11 to be associated with increased diabetes risk." (PMID 30169531, 2018).